ENSG00000203546 (novel protein)
Gene: Protein-coding gene on chromosome 14 (31,334,312 to 31,457,441, reverse strand). Ensembl gene ENSG00000203546.
Genetic constraint (gnomAD): Loss-of-function variants: 4 observed, 6.16 expected, observed/expected ratio (o/e) 0.65, 90% interval 0.32 to 1.46. That is too few expected variants to judge how well the gene tolerates losing a copy. Missense variants: 56 observed, 54 expected, observed/expected ratio (o/e) 1.04, 90% interval 0.84 to 1.3. Synonymous variants: 20 observed, 18.21 expected, observed/expected ratio (o/e) 1.1, 90% interval 0.77 to 1.59.